LINC02084 (long independently transcribed non-coding RNA 2084)
Gene: Long non-coding RNA gene on chromosome 3 (27,677,819 to 27,715,214, forward strand). Ensembl gene ENSG00000272282.
Diseases named in the same sentence as LINC02084 in open-access papers:
LINC02084 is named in the same sentence as 7 diseases in open-access papers, as found by Europe PMC text mining. Sharing a sentence is not in itself a finding about the gene and the disease. The quoted sentences say what the papers report.
colon cancer (2 papers, 2023 to 2025). "Furthermore, LINC02084 was used as a risk predictor in kidney renal clear cell carcinoma, colon cancer, and hepatocellular carcinoma." (PMID 38017579, 2023). "For example, women with versus without S. haematobium infection had upregulation of LINC02084, a long non-coding RNA associated with proliferation and cancer progression and a risk predictor in several cancers, including head and neck, renal cell and colon cancer." (PMID 41270010, 2025).
hepatocellular carcinoma (2 papers, 2022 to 2023). A malignant tumor that arises from hepatocytes. "LINC02084 has been previously linked to the prognoses of patients with hepatocellular carcinoma." (PMID 36280825, 2022).
breast carcinoma (1 paper, 2021). "Using these HRLs, we finally constructed a novel prognostic model for patients with breast cancer, which consisted of 12 PHRLs: TDRKH-AS1, AC011978.2, AC110995.1, OTUD6B-AS1, YTHDF3-AS1, AL512380.1, MIR4435-2HG, HSD11B1-AS1, LINC02084, TRG-AS1, AL451085.3, and AL109955.1 (RBM38-AS1)." (PMID 34977036, 2021).
COVID-19 (1 paper, 2021). A disease caused by infection with severe acute respiratory syndrome coronavirus 2. "It has been observed that increased level of LINC02207, LINC01127 was associated with the severe COVID-19 group, whereas LINC02084, LINC02446, LINC00861, LINC01871, and ANKRD44-AS1 were associated with the mild COVID-19 group." (PMID 34940755, 2021).
LINC02084 also shares sentences with these, for which no sentence is quoted: tumor (2 papers); cancer (1); Graves disease (1).